INS (insulin)
Diseases named in the same sentence as INS in open-access papers (continued):
Sharing a sentence is not in itself a finding about the gene and the disease.
diabetes (continued). "We also found that two IO-related genes including TRFC and SLC11A2, were down-regulated in patients with diabetes and were closely associated with genes related to insulin-secretion." (PMID 37344885, 2023). "Other T2D-associated SNPs have also been identified on JAZF1, many of which have additionally been linked to diabetes-relevant metabolic traits such as insulin secretion, insulin clearance, plasma lipid levels and body weight." (PMID 37091973, 2023). "Asians had higher levels of postprandial glycemia and lower insulin sensitivity than Whites in response to a realistic carbohydrate load, implying a prevalent genetic predisposition to insulin resistance and diabetes in Asians than whites." (PMID 37438808, 2023). "As such, these exerkines are implicated in improving insulin sensitivity and preventing obesity and diabetes mellitus with exercise." (PMID 37123278, 2023). "The underlying cause of the diabetes is related to the insufficient production of insulin or the improper response of the body to the insulin, which lead to increased blood glucose levels." (PMID 36939052, 2023). "Alternatively, diabetes can also result from the resistance of target tissues to the metabolic effects of insulin, which is commonly associated with obesity (known as type 2 diabetes or non-insulin-dependent diabetes mellitus)." (PMID 38132485, 2023). "Type 1 diabetes (T1D) is a chronic autoimmune condition in which the immune system attacks β-cells in the pancreas that causes a failure of producing insulin and subsequent hyperglycemia, which accounts for 5–10% of all diabetes cases." (PMID 38040681, 2023). "HbA1c-adjusted HR for the association between diabetes on insulin and a higher risk of major bleeding was 1.81 (95% CI 0.95–3.44, p = 0.071 vs diabetes not on insulin)." (PMID 35976428, 2023). "Regarding insulin secretion and pancreatic development, genome-wide association studies (GWAS) revealed genes that are related to diabetes mellitus." (PMID 37049638, 2023). "Disruption in hepatic glycogen metabolism as a result of metabolic dysfunction by insulin insensitivity has been associated with type 2 diabetes mellitus (T2D)." (PMID 37143025, 2023). "Diabetes Mellitus (DM) occurs due to inadequate utilization of insulin or insufficient insulin production caused by pancreatic injury or disease, resulting in reduced insulin availability." (PMID 37759824, 2023). "This is associated with decreased adiposity, which although protective of diabetes by itself, is overridden by loss of insulin secretion, resulting in diseases such as HH that are associated with high diabetes risk." (PMID 36137277, 2023). "This aligns with numerous publications describing obesity and overweight as implicated in the pathogenesis of type 2 diabetes mellitus through the pathway of insulin resistance." (PMID 38034219, 2023). "In the UKPDS study, the patients receiving metformin, insulin, and sulfonylureas compared to the patients undergoing conventional treatment had a lower risk for all the diabetes endpoints (−30%, p = 0.020), including stroke." (PMID 37513978, 2023). "Both T1DM and T2DM are caused by insufficient insulin action in the target tissues, and pancreatic beta cells are key players in the development of diabetes." (PMID 37761031, 2023). "Frequent insulin injections remain the primary method for controlling the blood glucose level of individuals with diabetes mellitus but are associated with low compliance." (PMID 37485249, 2023). "With recent advances over the last few years, such as better safety profiles in insulin pharmacokinetics and new diabetes devices, the risk of hypoglycemia has been reduced, and patients have been able to achieve better HbA1c goals." (PMID 37610810, 2023). "Diabetes mellitus is a prevalent chronic disease characterized by chronic hyperglycemia resulting from various causes of defective insulin secretion or defective insulin action that leads to abnormal metabolism of glucose, protein, and fat." (PMID 37694124, 2023).
diabetes (continued). "Consuming fast food has also been linked with poor health outcomes in children and adolescents including weight gain/obesity, increased risk of cardiovascular disease, difficulties in insulin functioning, and diabetes." (PMID 36959572, 2023). "This rare type of diabetes is characterized by impaired insulin secretion due to mutations in a transcription factor involved in beta cell differentiation and function." (PMID 37509590, 2023). "STZ causes symptoms resembling those of diabetes by destroying insulin-secreting pancreatic beta-cells and decreasing insulin production." (PMID 37842332, 2023). "Diabetes mellitus is a metabolic disorder characterized by abnormal carbohydrate metabolism caused by a deficiency in insulin secretion, insulin function, or both." (PMID 37229418, 2023). "The development of diabetes is typically linked to the disruption of the pancreas-insulin axis and the improper utilization of insulin." (PMID 38198642, 2023). "Diabetes is a chronic disease caused by a relative or absolute deficiency of insulin, reduced insulin sensitivity of target cells, and disturbances in glycolipid and protein metabolism." (PMID 37686368, 2023). "Diabetes is a medical condition characterized by chronic hyperglycemia caused by impaired insulin secretion or action." (PMID 37927670, 2023). "In the present investigation based on real-world clinical practice, we observed that insulin-requiring diabetes was associated with a very similar 2.35-fold elevation of MI." (PMID 35976428, 2023). "Studies conducted in different communities have used different ligation methods or HOMA to investigate the association between insulin resistance or impaired insulin secretion and pre-diabetes subtypes and also have produced different results." (PMID 36788521, 2023). "In the population of people with diabetes, individuals with T1D on basal–bolus insulin therapy have the greatest risk of hypoglycemia." (PMID 37888065, 2023). "In the subgroup analysis based on the type and number of anti-diabetic medications (one oral medication, 2 or more oral medications, and insulin use), it was confirmed that insulin users had a high risk of AP occurrence in diabetes patients." (PMID 37208706, 2023). "cg10217853, located within ARRDC4, has been identified as a novel CpG site in this study, and arrestin domain–containing protein 4 is associated with diabetes by regulating insulin resistance and lipid metabolism in β cells in response to glucose." (PMID 38137029, 2023). "XA was found to form complexes with insulin and to reduce its activity, thus predisposing rats to diabetes." (PMID 36766803, 2023). "The risk of diabetes is elevated by PC because it promotes the secretion of insulin that leads to insulin resistance." (PMID 36860363, 2023). "Diabetes mellitus is a chronic metabolic disorder caused either by inadequate insulin secretion, impaired insulin function, or both." (PMID 37032781, 2023). "Type 2 diabetes mellitus (T2DM) is caused by insulin resistance or tissue insensitivity to insulin, as well as relative insulin insufficiency." (PMID 38001474, 2023). "In the current study, we investigated the frequency of HU and its risk factors among insulin treated patients with diabetes in Madinah, KSA." (PMID 37964960, 2023). "In adjusted model 1, after adjusting for sex, HbA1c, TG, TC, HDL, LDL, smoking history, education level, duration of diabetes, and ever insulin use, the significant associations were attenuated and reserved." (PMID 37096235, 2023). "In fact, ethnic groups presenting a reduction in insulin clearance present a higher risk of developing type 2 diabetes mellitus." (PMID 36675244, 2023). "Loss of insulin secretion is a hallmark of all common forms of diabetes and also associated with iron-related diabetes resulting from either pathologic iron overload or dietary excess." (PMID 36137277, 2023).
diabetes (continued). "It is characterized by impaired glucose and lipid metabolism in insulin-sensitive tissues, mainly the skeletal muscle, liver and adipose tissue, leading to establishment of persistent hyperglycemia, the hallmark of diabetes." (PMID 36677541, 2023). "Increased levels of HbA1c and insulin dose are associated with increased diastolic blood pressure and HR in children with type 1 diabetes mellitus." (PMID 36991469, 2023). "On the one hand, it improves energy balance and reduces adiposity and, in addition to this, it improves insulin sensitivity and glucose homeostasis, which helps improve the metabolic profile of people who do it and reduce the risk of diabetes." (PMID 38111613, 2023). "The complexities of diabetes become more apparent when examining its molecular aspects, where hereditary and environmental variables interact to cause abnormalities in insulin signaling pathways." (PMID 38283440, 2023). "Hyperglycemia, which is a chronic condition caused by either insulin secretion problems or insulin resistance, is a hallmark of diabetes mellitus (DM)." (PMID 37111281, 2023). "It is reported that OSA impairs glucose-induced insulin secretion from pancreatic β cells and causes the aggregation of inflammatory factors in adipose tissue, leading to the occurrence of diabetes or insulin resistance (IR)." (PMID 35257355, 2023). "Cognitive dysfunction and impaired synaptic plasticity in both types of diabetes have been associated with hyperglycemia, insulin deficiency, and/or insulin resistance and altered insulin signaling." (PMID 37081849, 2023). "The down-regulation of glucose transporter type 4 in adipocytes, reduced insulin signaling, and impaired Ca2+ signaling in pancreatic -cells are some of the mechanisms implicated in the development of type 2 diabetes mellitus." (PMID 37185729, 2023). "Diabetes mellitus (DM), a chronic endocrine condition, is distinguished by persistent hyperglycemia caused by the body's inability to make or use insulin efficiently." (PMID 37441954, 2023). "It is widely understood that BBB disruption caused by diabetes can impact how glucose and insulin are transported into neurons and glia, resulting in cognitive impairment and, consequently, AD development." (PMID 37511207, 2023). "When looking into the validated proxy, rs757110 was associated with decreased type 2 diabetes mellitus risk and increased insulin secretion, consistent with the drug mechanism of actions." (PMID 37777789, 2023). "In our sample, insulin therapy, comorbidities and diabetes-related complications were also linked with worse diabetes self-management." (PMID 36809582, 2023). "One major contributor to the loss of insulin secretory capacity in diabetes caused by high iron is oxidative stress." (PMID 36137277, 2023). "This is the first comprehensive study to report on the effects of myostatin pharmacologic inhibition on an insulin‐deficient model of diabetes and describe these effects on both muscle and bone." (PMID 38025035, 2023). "This study investigated the possible link between cancer and the prospective development of type 2 diabetes, insulin treatment, and diabetes-associated complications during a 10-year follow-up period." (PMID 36831436, 2023). "These bioactive constituents exhibit the capacity to intervene in the crucial pathways associated with glucose homeostasis, insulin sensitivity, and the prevention or alleviation of diabetes-related complications." (PMID 37763235, 2023). "Diabetes mellitus (DM) is a complex and multifactorial disease characterized by progressive and chronic metabolic impairment due to the loss of insulin production and secretion from beta cells in the pancreas." (PMID 37153108, 2023). "Of note, both vegetable intake and Mediterranean diet style are associated with a decreased risk of post-transplantation diabetes, suggesting a favorable effect on insulin sensitivity." (PMID 38025208, 2023).
diabetes (continued). "Diabetes mellitus type 2 (DM 2): caused by a progressive loss of insulin secretion from β-cells during the course of the disease." (PMID 37892656, 2023). "Janghorbani and colleagues found increased risk of progression to PDR in insulin‐treated participants with 12 or more years' duration of diabetes." (PMID 36815723, 2023). "In particular, the inhibition of the Parkin gene can be a new alternative as an effective diabetes suppression that can significantly restore the decrease in insulin secretion caused by diabetic stress." (PMID 37134105, 2023). "Type 2 diabetes mellitus (T2D) indicates elevated blood glucose levels caused by the impairment of insulin secretion and insulin resistance." (PMID 36769060, 2023). "Based on findings linked to the role of vitamin D in insulin generation and glucose homeostasis, studies have demonstrated a causal relationship between vitamin D deficiency and diabetes mellitus." (PMID 37324274, 2023). "The insulin minisatellite region is the insulin-linked polymorphic region (ILPR), the polymorphism length of which is strongly linked to the genetic susceptibility of insulin-dependent diabetes mellitus (IDDM)." (PMID 37021044, 2023). "The pathophysiology of diabetes mellitus is closely associated with two essential factors, i.e., insulin levels and the body's ability to utilize this hormone." (PMID 37346355, 2023). "There are rare cases in which an inhibitory syndrome appears, caused by the suppression of insulin, exocrine pancreatic enzymes and cholecystokinin, characterized by the triad of diabetes mellitus, steatorrhea and cholelithiasis." (PMID 37628857, 2023). "Their results showed that participants in this plant-based diet experienced not only weight loss but also improved insulin sensitivity, a crucial factor in diabetes management." (PMID 38201865, 2023). "When there is insufficient insulin production or utilization, which causes diabetes, computer programs make it easier to develop an IT system for identifying diseases based on clinical data." (PMID 36832207, 2023). "Insulin use, diabetes, and Period1 were associated with significantly increased counts of hyperglycaemic events (glycaemia > 1.8 g/L) as yielded by negative binomial regression." (PMID 37330419, 2023). "In sum, although early studies underlined that the IDE plays a crucial role in insulin metabolism, its pharmacological inhibition as a strategy to treat diabetes has cast considerable doubts." (PMID 37892174, 2023). "Our result is consistent with a prior observation that overexpression of CDK4-R24C under the insulin promoter rescued diabetes due to leptin receptor deficiency." (PMID 37712417, 2023). "Recent research identified a close association between AD and diabetes whereby impaired insulin signaling in the brain results in similar pathophysiological characteristics of sAD." (PMID 38260013, 2023). "This non-significant difference (p=0.0766) is in good agreement with previous studies showing that BIL was liver-preferential and caused fewer hypoglycaemic events than conventional insulin treatment in individuals with diabetes." (PMID 36404376, 2023). "Most health organizations point to dietary interventions as a powerful treatment for diabetes, with controlled diets improving insulin sensitivity and reducing the risk of diabetes and its complications." (PMID 36839280, 2023). "Whole grains, fruits, and vegetables can reduce the risk of developing diabetes and its related complications by improving insulin and glucose metabolism." (PMID 37816701, 2023). "Of note, the excess stroke/TIA/systemic embolism in patients with insulin-requiring diabetes was paralleled by a consistent increase in all-cause death and cardiovascular death." (PMID 35976428, 2023).
diabetes (continued). "It has been shown that surrogate markers of liver fat and their change over time predict diabetes, whereas substantial weight loss from use of low-energy diets can lead to rapid fat loss from the liver and improved insulin sensitivity in people with diabetes." (PMID 36224274, 2023). "Insulin-treated diabetes mellitus and eGFR were identified as the risk factors of discordance between FFR- and iFR/RFR+." (PMID 36826530, 2023). "It includes four risk factors: pre-op number of diabetes medications, pre-op insulin use, pre-op duration of diabetes (years), pre-op glycemic control (<7%) and T2DM remission rate is expected to be higher after metabolic surgery in patient with mild severity." (PMID 36819346, 2023). "SM 42:2;2 was the sole lipid associated with lower risk on progression towards to insulin, but was associated with increased risk on future diabetes in the external validation data." (PMID 37137910, 2023). "Nevertheless, the tight control of hormonal regulations, including, by insulin and glucagon, ensure the proper function of neonatal liver with minimal risk of developing diabetes despite the high metabolic load." (PMID 37826876, 2023). "In humans, mutations in genes encoding insulin signaling proteins are also manifested by an increase in circulating insulin levels in the blood and are the causes of hereditary forms of diabetes." (PMID 36902173, 2023). "Despite the advances in diabetes management, HU continues to be prevalent among diabetic patients on insulin, and poor diabetes knowledge is a major risk factor." (PMID 37964960, 2023). "This is further fueled by advanced glycation end products (AGEs), and other oxidative pathways are deeply involved in the metabolic dysregulation associated with obesity, glucose metabolism, insulin signaling and development of diabetes." (PMID 35458674, 2022). "Non-pharmacological daily activities (e.g., diet, exercise, and weight loss) and pharmaceutical alternatives (e.g., insulin stimulators, insulin inhibitors, and glucosidase inhibitors) are two strategies for lowering diabetes prevalence." (PMID 35898909, 2022). "One of the risk factors for diabetes is obesity, and menopause is expected to be associated with diabetes in women, as it is accompanied by changes in body composition, glucose metabolism, and insulin sensitivity." (PMID 35455827, 2022). "We showed that Cdc42 functions as a regulator of diabetes-associated tissue injury, manifesting as an insulin secretion disorder with podocyte apoptosis." (PMID 36034435, 2022). "When considering the still-growing amount of diabetes causes and the importance of the accurate systems of direct insulin measurements in the human body, new electrochemical sensors for insulin determination are still demanded." (PMID 36557132, 2022). "Diabetes mellitus (DM) is a chronic metabolic disease associated with hyperglycemia owing to impaired insulin secretion, insulin activity, or both." (PMID 35957831, 2022). "Diabetes mellitus (DM) is a group of metabolic diseases characterised by the long-term increase in blood glucose levels due to the deficiency of insulin secretion." (PMID 35438580, 2022). "Insufficient insulin production or insulin activity produces elevated blood glucose levels and causes diabetes mellitus." (PMID 35741464, 2022). "The association of metabolic syndrome, hypertension, obesity, diabetes, impaired glucose tolerance, and elevated insulin levels with prolonged QTc and the effect other factors discussed earlier on QT intervals and cardiovascular events should not be ignored." (PMID 35172723, 2022). "Osteopenia and bone fragility are some of the problems faced by many people with diabetes, which are caused either by residual insulin secretion or high insulin requirements." (PMID 35956932, 2022). "The American Diabetes Association recommends that patients treated with insulin who are unaware of hypoglycemia should be counseled on signs and methods to treat it." (PMID 35156937, 2022).